HCK (HCK proto-oncogene, Src family tyrosine kinase)
Diseases named in the same sentence as HCK in open-access papers (continued):
Sharing a sentence is not in itself a finding about the gene and the disease.
membranous nephropathy (1 paper, 2026). "Proteomic-wide MR revealed MTR as protective in chronic GN and HCK as a risk factor for membranous nephropathy, whereas CD302 and CDKN1B showed protective effects." (PMID 41990104, 2026).
metastatic tumors (1 paper, 2020). "The ratio of HCK expression in metastatic tumor was also higher than that in primary tumor." (PMID 33162805, 2020).
myeloid leukemia (1 paper, 2021). A clonal proliferation of myeloid cells and their precursors in the bone marrow, peripheral blood, and spleen. "On the other hand, HCK gene and protein depletion, in presence or absence of AMD3100, caused a reduction of action polymerization in human myeloid leukemia cell lines compared to control or cells treated with vehicle." (PMID 33842460, 2021).
myocardial infarction (1 paper, 2019). Gross necrosis of the myocardium, as a result of interruption of the blood supply to the area, as in coronary thrombosis. "Six hub genes, including BCL3, HCK, PPIF, S100A9, SERPINA1, and TBC1D9B that differentiated on admission after myocardial infarction the HF patients from the non-HF ones, can serve as early prognostic biomarkers of post-AMI patients." (PMID 31850068, 2019).
oral cancer (1 paper, 2025). "The genes PPT1 (palmitoyl-protein thioesterase 1), LILRA4 (leukocyte immunoglobulin-like receptor A4), and HCK (hemopoietic cell kinase) were correlated with a lower risk of oral cancer, while TNFRSF13C (tumor necrosis factor receptor superfamily member 13c) was linked to a higher risk." (PMID 40521000, 2025).
osteoporosis (1 paper, 2021). A condition of reduced bone mass, with decreased cortical thickness and a decrease in the number and size of the trabeculae of cancellous bone (but normal chemical composition), resulting in increased fracture incidence. "A 5-gene combination (CCR1, CD33, HCK, LILRB2 and CYBB) was established as an optimal and effective biomarker for osteoporosis using SVM with feature selection and classification procedures." (PMID 34622712, 2021).
polycythemia (1 paper, 2019). Abnormally high mass or concentration of red blood cells in the blood, either due to an increase in erythropoiesis or a decrease in plasma volume. "To summarize, the combination of HCK overexpression and PTPRT loss was associated with some myeloproliferative characteristics such as hyperproliferation and STAT3 upregulation in vitro, and aberrant bone marrow erythroid maturation, polycythemia and splenomegaly in vivo." (PMID 31065022, 2019). "The three characteristics appeared to be strongly correlated and supports the hypothesis that HCK amplification on the background of PTPRT depletion had directly resulted in aberrant bone marrow erythroid development, which subsequently led to the establishment of polycythemia and splenomegaly." (PMID 31065022, 2019).
pulmonary fibrosis (1 paper, 2025). Chronic progressive interstitial lung disorder characterized by the replacement of the lung tissue by connective tissue, leading to progressive dyspnea, respiratory failure, or right heart failure. "Increasing evidence suggests that Src family kinases (SFKs), including SRC and HCK, which are strongly correlated with ADAM15, are involved in the pathogenesis of pulmonary fibrosis." (PMID 39824903, 2025).
sarcoidosis (1 paper, 2022). Sarcoidosis is a multisystemic disorder of unknown cause characterized by the formation of immune granulomas in involved organs. "However, some UIC STAR cohort key determinant genes, such as ATP6V0D1, FTH1, G6PD, HCK, and SPI1 have been previously associated with sarcoidosis in other studies." (PMID 36311769, 2022).
Splenomegaly (1 paper, 2019). Abnormal increased size of the spleen. "One out of three recipients of PTPRT−/− HSCs transduced with either HCK or MIGR1 control developed splenomegaly." (PMID 31065022, 2019).
systemic lupus erythematosus (1 paper, 2020). An autoimmune multi-organ disease typically associated with vasculopathy and autoantibody production. "In the third trimester, systemic lupus erythematosus and proteasome were enriched in the acute disease while Fc gamma R-mediated phagocytosis (VAV1, MARCKSL1, WASF2, DNM2, HCK, MAP2K1 genes) and adherens junction (ACTG1, WASF2, SMAD4, CSNK2B, EP300 genes) represented the subclinical category." (PMID 32012176, 2020).
systemic vasculitis (1 paper, 2026). "In Family A, we report a child with systemic vasculitis due to a nonsense heterozygous variant in HCK (p.Y515X) who was subsequently treated with allogeneic haematopoietic stem cell transplantation (allo-HSCT), the first use of this approach in SFK-related disease." (PMID 41920357, 2026).
thyroid cancer (1 paper, 2016). "BTK and HCK expressions are upregulated in invasive thyroid cancer compared to matched normal group, which is similar to Src." (PMID 27703281, 2016).
triple-negative breast carcinoma (1 paper, 2020). An invasive breast carcinoma which is negative for expression of estrogen receptor (ER), progesterone receptor (PR), and human epidermal growth factor receptor 2 (HER2). "We further found that patients with triple negative breast cancer-immunomodulatory subclasses had the highest HCK mRNA expression among all these subclasses (P<0.01)." (PMID 33162805, 2020).
Ureteral obstruction (1 paper, 2023). Obstruction of the flow of urine through the ureter. "In vivo, both global or myeloid cell specific HCK-KO attenuates renal inflammation and fibrosis with reduces macrophage numbers, pro-inflammatory polarization and migration into unilateral ureteral obstruction (UUO) kidneys and unilateral ischemia reperfusion injury (IRI) models." (PMID 37463911, 2023).
tumor (35 papers, 2011 to 2026). "The results indicated that HCK was associated with a variety of infiltrated immune cells, including B cells, T cells, NK cells, monocytes, plasma cells, mast cells, tumor-associated macrophages (TAMs), and neutrophils." (PMID 35280440, 2022). "HCK plays important roles in inflammatory response and is activated in tumor-associated immune cells." (PMID 33041826, 2020). "HCK caused an augment of cell viability, proliferation, migration, and tumor growth, and induced cell apoptosis." (PMID 32484210, 2020). "Within tumor associated macrophages, HCK stimulates the formation of podosomes that facilitate extracellular matrix degradation, which enhance immune and epithelial cell invasion." (PMID 26087188, 2015). "Given the role of stromal cells as key enablers and enhancers of many of the hallmarks of cancer, we predict that the inhibition of HCK in tumor-associated innate immune cells will reduce their ability to promote angiogenesis, inflammation, migration and invasion." (PMID 26087188, 2015). "In addition, CIBERSORT analysis showed that HCK was closely related to tumor immune infiltration, with HCK expression associated with various infiltrating immune cells, including B cells, T cells, tumor-associated macrophages (TAM), NK cells, plasma cells, eosinophils, and neutrophils." (PMID 35280440, 2022). "Our results show that NCFs and their coexpressed genes, including SPI1, HCK, VAV1, CD53, and ITGB2, are significantly associated with tumor-infiltrating immune cells, especially with immunosuppressive macrophages." (PMID 34708124, 2021). "The volume and weight of tumours were markedly decreased in mice transplanted with shHCK‐transfected U‐2 OS cells compared with control mice, indicating that HCK expression promotes OS tumorigenesis." (PMID 34363435, 2021). "We found that downregulation of HCK resulted in increased apoptosis in and reduced proliferation and migration of OS cells in vitro as well as tumour growth in vivo via suppression of EMT." (PMID 34363435, 2021). "A total of 163 tumor samples from GBM patients and 207 normal samples were analyzed, and we found that HCK was highly expressed in tumor samples compared with control samples." (PMID 32484210, 2020). "Our results revealed that inhibition of HCK led to the decrease in cell viability, migration, and tumor growth, as well as the increase in cell apoptosis via inhibiting EMT." (PMID 32484210, 2020). "In the present study, HCK was demonstrated to be highly expressed in both tumor tissues from patients with GBM and GBM cell lines." (PMID 32484210, 2020). "For DFS, tumor size and HCK expression were related to DFS in univariate cox regression analysis (P<0.001; P=0.003), and thus they were entered into multivariate cox regression analysis." (PMID 33162805, 2020). "The present study found that HCK was highly expressed in both tumor tissues from patients with GBM and cancer cell lines." (PMID 32484210, 2020). "The results showed that the tumor size was smaller in mice with HCK inhibition than that in control mice." (PMID 32484210, 2020). "For OS, tumor size, Ki67 index, and HCK expression were related to OS (P=0.001; P=0.004; P=0.001) in univariate cox regression analysis, and thus they were entered into multivariate cox regression analysis." (PMID 33162805, 2020). "The present study demonstrated that HCK was highly expressed in tumor tissues from patients with GBM and GBM cell lines." (PMID 32484210, 2020). "IL6R, PLCG1, PTPN1, and HCK are involved in cytokine/interferon signaling to activate immune cells to counter proliferating tumor cells." (PMID 30978274, 2019). "Recent study also postulated that the hematopoietic cell kinase (HCK), which belongs to the Src kinase family is constitutively expressed on myeloid cells and associated with tumour initiation and survival." (PMID 29455663, 2018).
tumor (continued). "The emergence of this tyrosine kinase for macrophage polarization supports the potential use of SFK-inhibitor such as dasatinib and imatinib, to reprogram the immunosuppressive macrophages to anti-tumour phenotype through blunting the HCK activity of TAMs." (PMID 29455663, 2018). "Consistent with the in vitro results, study of cross-sections of DTX-treated tumours revealed the localization of phosphorylated HCK with CD44Hi cells." (PMID 25669750, 2015). "Given its known crystal structure, HCK therefore provides an attractive therapeutic target to both, directly inhibit the growth of cancer cells, and indirectly curb the source of tumor-promoting changes in the tumor microenvironment." (PMID 26087188, 2015). "Two strong candidates identified in this study are a tyrosine kinase, HCK, and a tumor suppressor, BIN1, which show upregulation at both RNA and protein levels in AHI-1-suppressed CTCL cells." (PMID 22248740, 2011). "Consistent with a role for HCK in macrophage invasiveness, plasma membrane-associated Src family kinase activity at the tumor margins was lost in the absence of HCK." (PMID 41789109, 2026). "By simultaneously targeting both HCK and IDO1, DAU intervenes in two pathways, one modulating immune cell phenotype and the other regulating ferroptosis susceptibility, thereby creating a synergistic anti‐tumor effect in BLCA." (PMID 41438182, 2025). "In this co-invasion assay, selective inhibition of either HCK or PI3K p110δ are equally as effective as CSF-1R inhibition in shutting down macrophage-led tumor cell invasion while macrophages expressing constitutively active HCK promote increase tumor cell invasion." (PMID 39588367, 2024). "In addition, inflammatory mediators secreted by the tumor cell immune microenvironment can induce HCK activation in macrophages and neutrophils, promoting tumor expansion and invasion." (PMID 35280440, 2022). "The hypermethylated/downregulated gene HCK was just a tumor suppressor gene." (PMID 33833773, 2021). "Furthermore, HCK downregulation decreased the tumour volume and weight in mice transplanted with OS cells." (PMID 34363435, 2021). "HCK activation may indirectly promoting tumor progression through cytokine secretion in tumor-related immune cells, except its direct oncogenic role in cancer cells." (PMID 32484210, 2020). "Tumor xenografts results also demonstrated that HCK knockdown significantly inhibited tumor growth." (PMID 32484210, 2020). "HCK enhances the secretion of growth factors and pro-inflammatory cytokines from myeloid cells, and promotes macrophage polarization towards a wound healing and tumor-promoting alternatively activated phenotype." (PMID 26087188, 2015). "Thus, while HCK has a direct role in promoting some blood-derived cancers, its aberrant activation in innate immune cells of the tumor microenvironment facilitates tumorigenesis and enables progression in experimental models and in human cancers." (PMID 26087188, 2015). "Therefore, in addition to its direct carcinogenic effects on leukemia cancer cells, early tumor cells can stimulate excessive activation of HCK in adjacent immune cells by promoting cytokine secretion, to strengthen the role of tumor-promoting microenvironment." (PMID 35280440, 2022). "However, HCK activity either alone or within the context of other SFKs often reduces the efficacy of recombinant immunotoxins, where antibody fragments are tethered to an exotoxin that induces apoptosis upon antigene binding to the surface of tumor cells." (PMID 26087188, 2015). "In BLCA cells, DAU also impacts the downstream target of HCK/IDO1, which inhibits tumor progression by promoting ferroptosis and ferritinophagy." (PMID 41438182, 2025). "The IHC staining results of 30 tumor tissue samples from BLCA patients provided by Yanbian University Hospital also showed a positive correlation between the expression of CD206, HCK, and IDO1." (PMID 41438182, 2025).
tumor (continued). "DAU impacts the downstream target of HCK/IDO1, which inhibits tumor progression by promoting ferritinophagy." (PMID 41438182, 2025). "These metagene clusters (HCK, Interferon, MHC-I, MHC-II, IgG, LCK, and STAT1) have previously been reported to represent various tumor inflammatory activities." (PMID 36439943, 2022). "ANKRD13B, ISG15, KBTBD12, KLHL35, and UHRF1 were upregulated in tumor samples; DCUN1D5, HCK, and SOCS3 were downregulated in tumor than in normal samples." (PMID 35884544, 2022). "These upregulated sites included two clinical drug targets annotated as Src-family kinases (HCK and LYN), which were reported to promote tumor malignancy in NSCLC43." (PMID 33953186, 2021). "HCK inhibition decreases tumor growth, perhaps by impairing TGFBeta-SMAD signaling pathways or STAT3-dependent tumor growth." (PMID 33233470, 2020). "For example, Src family kinases HCK, FRK and LYN are onco-homologs of PDGFRA/KIT, which interact with both PDGFRA and KIT as downstream effectors and play critical roles in tumor cell proliferation and survival." (PMID 29844492, 2018). "Thus, in addition to its direct oncogenic role in (leukemic) cancer cells, excessive HCK activation may be stimulated in neighboring immune cells by incipient tumor cells through cytokine secretion thereby reinforcing a tumor-enabling and tumor-promoting microenvironment." (PMID 26087188, 2015). "Other emerging SFK inhibitors with high specificity against HCK include A-419259, which blocks proliferation and induces apoptosis in CML cell lines, as well as RK-20449, which promotes tumor regression in a mouse xenograft model." (PMID 26087188, 2015). "In addition, a seven-metagene cluster (STAT1, interferon, HCK, MHC-I, MHC-II, IgG, and LCK) has been reported in several studies to illustrate the inflammatory activities in the tumor microenvironment." (PMID 35222371, 2022). "Using the dataset, we found that the level of HCK promoter methylation was significantly higher in primary tumor than in non-cancer tissues (P<0.01)." (PMID 33162805, 2020). "Hematopoietic cell kinase (HCK), which belongs to the SRC family of non-receptor protein tyrosine kinases (SFK), is primarily expressed in B lymphocyte lineages and cells of myeloid and is the most abundantly expressed SFKs in the tumor-associated host stroma 8,9." (PMID 33162805, 2020). "In our study, we also found a negative correlation between LIGHT expression and tumor purity, and a positive correlation between LIGHT expression and immunity metagenes, excluding IgG, such as HCK and interferon, was observed." (PMID 36341396, 2022).